SMC6 (structural maintenance of chromosomes 6)
Description:
Core component of the SMC5-SMC6 complex, a complex involved in DNA double-strand breaks by homologous recombination. The complex may promote sister chromatid homologous recombination by recruiting the SMC1-SMC3 cohesin complex to double-strand breaks. The complex is required for telomere maintenance via recombination in ALT (alternative lengthening of telomeres) cell lines and mediates sumoylation of shelterin complex (telosome) components which is proposed to lead to shelterin complex disassembly in ALT-associated PML bodies (APBs). Required for recruitment of telomeres to PML nuclear bodies. SMC5-SMC6 complex may prevent transcription of episomal DNA, such as circular viral DNA genome.
Synonyms: SMC-6; hSMC6; SMC6L1; FLJ22116
Tractability: PROTAC: UniProt records ubiquitination sites on it; ubiquitination databases record sites on it; its protein half-life has been measured.
Gene: Protein-coding gene on chromosome 2 (17,663,583 to 17,800,242, reverse strand). Ensembl gene ENSG00000163029.
Subcellular location: Nucleus; Nucleus speckle; Chromosome; Nucleus, PML body; Chromosome, telomere
Subcellular location (Human Protein Atlas): Nucleoplasm
Pathways (Reactome):
Metabolism of proteins: SUMOylation of DNA damage response and repair proteins
Gene Ontology:
Molecular function: DNA secondary structure binding; protein binding; ubiquitin protein ligase binding; damaged DNA binding; single-stranded DNA binding
Biological process: cellular senescence; DNA damage response; host-mediated suppression of viral genome replication; positive regulation of chromosome segregation; telomere maintenance via recombination; chromatin looping; double-strand break repair via homologous recombination; protein sumoylation; regulation of telomere maintenance
Cellular component: chromosome, telomeric region; interchromatin granule; nuclear speck; nucleoplasm; nucleus; PML body; site of double-strand break; Smc5-Smc6 complex; chromosome; sex chromosome; chromosomal region; chromosome, centromeric region; mitotic spindle pole
Genetic constraint (gnomAD): Loss-of-function variants: 53 observed, 94.26 expected, observed/expected ratio (o/e) 0.56, 90% interval 0.45 to 0.71. The upper end of that interval is the gene's LOEUF score, 0.71, which puts it in group 2 of 6, group 1 being the genes least tolerant of losing a copy. Missense variants: 789 observed, 929.41 expected, observed/expected ratio (o/e) 0.85, 90% interval 0.8 to 0.9. Synonymous variants: 288 observed, 301.68 expected, observed/expected ratio (o/e) 0.95, 90% interval 0.87 to 1.05.
Homologues: Orthologues: chimpanzee SMC6 (99% identical), macaque SMC6 (98% identical), dog SMC6 (93% identical), pig SMC6 (92% identical), rat Smc6 (91% identical), guinea pig SMC6 (91% identical), mouse Smc6 (91% identical), tropical clawed frog smc6 (59% identical), zebrafish si:dkey-119f1.1 (51% identical), Caenorhabditis elegans C23H4.6 (26% identical), Drosophila melanogaster SMC6 (26% identical), Caenorhabditis elegans smc-6 (23% identical). Paralogues in human: SMC5 (18% identical).
Diseases named in the same sentence as SMC6 in open-access papers:
SMC6 is named in the same sentence as 18 diseases in open-access papers, as found by Europe PMC text mining. Sharing a sentence is not in itself a finding about the gene and the disease. The quoted sentences say what the papers report.
colorectal cancer (2 papers, 2023 to 2024). A primary or metastatic malignant neoplasm that affects the colon or rectum. "In the HMF colorectal cancers, we discovered eight predictive gene deficiency models (MSH3, SMC2, SMC6, BMPR2, CLASP2, SRCAP, UBR5, and UVRAG) of monoallelic LOF with PR-AUC-E ranging from 0.21 (CLASP2) to 0.62 (MSH3) (AUROC ranging from 0.68 for SRCAP deficiency to 0.94 for MSH3 deficiency)." (PMID 36883553, 2023).
prostate carcinoma (2 papers, 2018 to 2024). A carcinoma that arises from epithelial cells of the prostate gland. "Thus, in the meta-analyses of prostate cancer, we explored two top gene sets whose GSAS were driven by ESM1, and by SMC6, CDT1 and RAD18." (PMID 38597610, 2024).
Bloom syndrome (1 paper, 2020). Bloom syndrome (BSyn) is a rare chromosomal breakage syndrome characterized by a marked genetic instability associated with pre- and postnatal growth retardation, facial sun-sensitive telangiectatic erythema, increased susceptibility to infections, and predisposition to cancer. "Furthermore, him-6 mutants, defective for the C. elegans orthologue of the BLM (Bloom syndrome) helicase, and smc-6 mutants, defective for the Smc5/6 cohesin-like complex, showed an increased incidence of SVs." (PMID 32358516, 2020).
cyst (1 paper, 2021). A sac-like closed membranous structure that may be empty or contain fluid or amorphous material. "Several of the meiotic-related genes change their expression in the cyst stage, including Hop1, Mre11, and Smc6, suggesting that the process continues until the end of the differentiation process." (PMID 34946882, 2021).
diabetes (1 paper, 2024). "There is no research on SMC4 and SMC6 in lung cancer and diabetes, which needs further exploration." (PMID 38468345, 2024).
gastric carcinoma (1 paper, 2022). A carcinoma that arises from epithelial cells of the stomach. "We observed SMC6 loss in AGS gastric carcinoma cells induced for lytic replication and suspect that BNRF1 has similarly important roles in support of epithelial cell lytic replication." (PMID 35263599, 2022).
latent infection (1 paper, 2022). "The reduction of H3K27ac on the RTA promoter by SMC6 promotes the repression of RTA during latency, indicating that SMC5/6 may play an important role in maintaining latent infection." (PMID 35914008, 2022).
lung carcinoma (1 paper, 2024). "In summary, SMC6, CDC27, CDC7, RACGAP1, SMC4, NCF1,2,4, SELPLG and CFP are significantly associated with T2DM and lung cancer, making them potential target genes for disease prediction and treatment in the future." (PMID 38468345, 2024).
sarcoma (1 paper, 2020). A usually aggressive malignant neoplasm of the soft tissue or bone. "We concluded that SMC1A, SMC2, SMC3, SMC4, SMC5 and SMC6 were all highly expressed in sarcoma cell lines." (PMID 33460400, 2020). "In our study, we found that SMC5 and SMC6 were both more highly expressed in sarcoma than in normal tissues, and also in human sarcoma cell lines." (PMID 33460400, 2020). "According to the Cancer Cell Line Encyclopedia (CCLE), SMC1A, SMC2, SMC3, SMC4, SMC5 and SMC6 are also highly expressed in sarcoma cell lines." (PMID 33460400, 2020). "GEPIA was used to investigate the prognostic ability of SMC1, SMC2, SMC3, SMC4, SMC5 and SMC6 expression in sarcoma." (PMID 33460400, 2020). "It was confirmed that the expression levels of SMC1A, SMC2, SMC3, SMC4, SMC5 and SMC6 in sarcoma were higher than in normal tissues." (PMID 33460400, 2020). "Our results also suggest that SMC1A and SMC2 are potential therapeutic targets for sarcoma, while levels of transcripts of SMC3, SMC4, SMC5 and SMC6 are potential prognostic markers to improve the survival rate and prognostic accuracy of sarcoma." (PMID 33460400, 2020). "We found that increased expression of SMC1A, SMC2, SMC3, SMC4, SMC5 and SMC6 might play a significant role in sarcoma tumorigenesis." (PMID 33460400, 2020). "In contrast, SMC3, SMC4, SMC5, and SMC6 expression had no significant impact on OS or DFS in sarcoma." (PMID 33460400, 2020). "However, only the overexpression of SMC1A and SMC2 was related to the OS of sarcoma patients, whereas SMC3, SMC4, SMC5 and SMC6 had no significant impact on prognosis." (PMID 33460400, 2020).
synovial sarcoma (1 paper, 2020). "This revealed that SMC1A, SMC2, SMC3, SMC4, SMC5 and SMC6 proteins were all more highly expressed in the synovial sarcoma tissues than in corresponding normal tissues." (PMID 33460400, 2020).
infection (6 papers, 2017 to 2023). The state of being infected such as from the introduction of a foreign agent such as serum, vaccine, antigenic substance or organism. "Depletion of SMC6, however, is associated with a slight change in number of viral genomes during Ad5 WT infection, compared to control siRNA treatment." (PMID 34463575, 2021). "For example, they will need to be tested for their ability to rescue HBx-deficient HBV replication in an infection model, as described for the SMC6 restriction factor." (PMID 32235678, 2020). "At 6 hours post-infection, we observed a significant reduction in SMC6 protein expression after B cell exposure to both wild-type virus and VLPs, but not after incubation with the ∆gp110-defective mutant." (PMID 37830871, 2023). "To test the potential inhibitory impact of SMARCAD1 and SMC6 proteins on Ad5 infection, we used small interfering RNA (siRNA) to deplete them individually prior to infection." (PMID 34463575, 2021). "The data assessing the impact of depletion of SMARCAD1, SMC5, or SMC6 on Ad5 infection suggest that these proteins exert inhibitory effects on productive Ad5 infection, which are more pronounced during AdΔE4 infection." (PMID 34463575, 2021). "During Ad5 WT infection, depletion of SMARCAD1, SMC5, or SMC6 is associated with 2- to 3-fold, statistically significant increases in PFU at 24 hpi compared to control siRNA treatment." (PMID 34463575, 2021). "However, SMC6 mRNA increased over the first 48 h after infection, suggesting that changes in its protein abundance likely occurred at the post-transcriptional level." (PMID 35263599, 2022). "We assessed the localization of SMC6 during mock, Ad5 WT, and AdΔE4 infections using IF." (PMID 34463575, 2021). "Since SMC5 is known to form a complex with SMC6, we also tested the impact of SMC5 depletion by siRNA on infection." (PMID 34463575, 2021). "Although the observed impacts of individual depletion of SMARCAD1, SMC5, or SMC6 were modest, this could be explained by redundancy within the host response since each of these proteins is part of families in which multiple members may be acting in a coordinated manner to inhibit infection." (PMID 34463575, 2021). "During infection with human papillomavirus, SMC5/6 was found to localize to viral replication foci and depletion of SMC6 decreased total viral DNA levels." (PMID 34463575, 2021). "RNA-Seq analysis revealed that HBx RNA can be detected very early after infection of PHH, prior to depletion of Smc6 and transcription of the other HBV genes." (PMID 28095508, 2017). "The iPOND and IF data suggest that SMARCAD1 and SMC6 localize to viral genomes, at VRCs, during infection with AdΔE4 but not with Ad5 WT virus." (PMID 34463575, 2021). "SMC6 exhibits diffuse nuclear and occasional perinuclear localizations during mock or Ad5 WT infection but exhibits striking reorganization to colocalize with DBP and BrdU at VRCs during AdΔE4 infection." (PMID 34463575, 2021). "During AdΔE4 infection, depletion of SMARCAD1 is associated with no change in number of viral genomes, while depletion of either SMC5 or SMC6 is associated with statistically significant increases in viral genomes at 48 hpi compared to control siRNA treatment." (PMID 34463575, 2021). "During AdΔE4 infection, depletion of SMARCAD1, SMC5, or SMC6 is associated with no change in PFU at 24 hpi but is associated with 2- to 4-fold, statistically significant increases in PFU at 48 hpi compared to control siRNA treatment." (PMID 34463575, 2021). "The immunoblotting data suggest that SMARCAD1 and SMC6 localizations at AdΔE4 viral replication centers are not driven by increased abundance during AdΔE4 infection." (PMID 34463575, 2021). "HBVΔX infection also did not induce coordinated ISG expression when cccDNA transcription was rescued by knock-down of Smc6 (siSmc6)." (PMID 28095508, 2017).
infection (continued). "During Ad5 WT or AdΔE4 infection, Ad5 hexon, penton, and fiber proteins show no meaningful change in abundance in the context of depletion of SMARCAD1, SMC5, or SMC6 compared to control siRNA treatment." (PMID 34463575, 2021). "It has previously been shown that infection of PHH by HBV, but not HBVΔX, leads to degradation of Smc5/6 and that knock-down of Smc6 rescues HBVΔX transcription." (PMID 28095508, 2017). "In contrast, Smc6 was degraded relatively quickly after infection, with >50% of HBV-infected PHH being Smc6-negative by day 2 post-infection (sum of red and blue bars)." (PMID 28095508, 2017). "While this finding agrees with another reporting that HPV-5/-18 and BPV-1 E2 proteins do not influence the SMC6 abundance, it contrasts with studies of hepatitis B virus (HBV) wherein the master regulatory protein of HBV—HBx—was found to target SMC5/6 for degradation shortly after infection." (PMID 32992873, 2020).
cancer (5 papers, 2016 to 2022). A tumor composed of atypical neoplastic, often pleomorphic cells that invade other tissues. "Interestingly, we found four genes (FXR1, RAD50, SP100, SMC6) mutated in 50% of the G1 LS-cancer samples, with the latter three belonging to the APB branch of the ALT-TMM pathway." (PMID 31750255, 2019). "For example, TBPT significantly suppressed a series of genes involved in DNA double-strand break repair, including LIG4, CENPF, DNAJC2, RECQL, SMC6 and BRCA2 (≥ 2-fold), which are also considered vital targets for treating cancer cells without affecting normal cells." (PMID 26986511, 2016).
tumor (2 papers, 2017 to 2021). "Compared with normal tissues, SMC6 has also been confirmed to have abnormal expression in lung cancer, sarcoma, and other tumor types." (PMID 34527684, 2021). "In addition, consistent with previous research results, we also found that SMC1A, SMC1B, SMC2, SMC3, SMC4, and SMC6 were overexpressed at the mRNA level in HCC when compared with non-tumor cells." (PMID 34527684, 2021).
bacterial infections (1 paper, 2022). "Comparison of these results with those obtained from bacterial infections showed genes associated with cell‐cycle progression and cell proliferation (RGCC, SENP5, SMC6, SERTAD3, MAD2L1BP) to be specifically upregulated in DC3s." (PMID 34333764, 2022).
SMC6 also shares sentences with these, for which no sentence is quoted: B‐cell lymphoma (1 paper); liver cancer (1); malignant fibrous histiocytoma (1); metastatic tumors (1).